AGRN (agrin)
Diseases named in the same sentence as AGRN in open-access papers (continued):
Sharing a sentence is not in itself a finding about the gene and the disease.
squamous cell carcinoma (3 papers, 2014 to 2025). A carcinoma arising from squamous epithelial cells. "The mRNA levels of agrin and perlecan were evaluated in cell lines with different sites of origin: oral squamous carcinoma cell line (SCC-9) isolated from tongue, oral squamous carcinoma cell line (SCC-9) isolated from lymph nodes (SCC-9 LN-1) and a skin-derived squamous carcinoma (A431)." (PMID 25506919, 2014). "Tier 2 proteins, supported by transcriptomic evidence but not sensitivity analyses, included AGRN, ITGB2, SEPTIN3 (adenocarcinoma) and DPP10 (squamous cell carcinoma)." (PMID 41340014, 2025).
thymoma (3 papers, 2017 to 2024). A neoplasm arising from the epithelial cells of the thymus. "Some Agrin-MG cases were accompanied by thymoma in our cohort, and these patients were successfully treated with a thymectomy." (PMID 34956185, 2021).
Arthritis (2 papers, 2013 to 2022). Inflammation of a joint. "In the present study, clinical-like cryotherapy after acute-induced knee joint inflammation increased Agrin expression, which possibly contributed to maintaining and protecting quadriceps NMJ and reducing inflammatory signs of synovial fluid (edema and neutrophil migration)." (PMID 35103239, 2022).
catecholaminergic polymorphic ventricular tachycardia (2 papers, 2023). Catecholaminergic polymorphic ventricular tachycardia (CPVT) is a severe genetic arrhythmogenic disorder characterized by adrenergically induced ventricular tachycardia (VT) manifesting as syncope and sudden death. "Recent evidence suggested a possible candidate gene, agrin (AGRN), for the catecholaminergic polymorphic ventricular tachycardia, though functional studies are necessary to fully understand their implications and the pathophysiology in CPVT." (PMID 38034271, 2023).
distal myopathy (2 papers, 2018 to 2022). Distal myopathy refers to a group of muscle diseases which share the clinical pattern of predominant weakness and atrophy beginning in the feet and/or hands. "Our two patients with AGRN mutations, consistent with other reported AGRN‐CMS Chinese patients, did not exhibit manifestations of distal myopathy." (PMID 35670010, 2022).
head and neck cancer (2 papers, 2018 to 2025). A primary or metastatic malignant neoplasm affecting the head and neck. "In conclusion, our results underscore agrin expression as a novel marker for malignant and premalignant oral lesions and indicates agrin contextual hubs as a prognostic signature for head and neck cancers." (PMID 29872149, 2018). "Since OSCC is the most common type of malignancy arising from the epithelial cells of the head and neck region, we evaluated a clinical relevance of agrin contextual hubs in head and neck cancers." (PMID 29872149, 2018). "Furthermore, AGRN overexpression was observed in other tumors, i.e., head and neck cancer, where it also played the role of a hub." (PMID 40136513, 2025). "Finally, we found that agrin interactome is related with clinical outcomes of head and neck cancers." (PMID 29872149, 2018).
injury (2 papers, 2025). Damage inflicted on the body as the direct or indirect result of an external force, with or without disruption of structural continuity. "Consequently, the upregulation of Agrin could have contributed to the neuroprotection observed after treatment with BRT_002 of neonatal rats exposed to HI-related brain injury." (PMID 40533307, 2025).
ischemia (2 papers, 2012 to 2021). A hypoperfusion of the BLOOD through an organ or tissue caused by a PATHOLOGIC CONSTRICTION or obstruction of its BLOOD VESSELS, or an absence of BLOOD CIRCULATION. "It has been reported that ischemia-induced MMP-3 processes agrin expressed in neurons and that processed agrin is released from tissue membrane fractions to tissue protein extracts." (PMID 22984437, 2012). "MMP-3 has previously been shown to cleave and remove agrin from the synaptic basal lamina and to process neuronal agrin following ischemia." (PMID 22984437, 2012).
lymph node metastasis (2 papers, 2018 to 2019). "Higher tumor tissue expressions of two proteins, AGRN and CTSC, were found to be significantly associated with lymph node metastasis, distant metastasis at diagnosis, and poor prognosis of PTC patients." (PMID 29552294, 2018). "Higher expression levels of AGRN and CTSC were found to be significantly correlated with lymph node metastasis, distant metastasis at diagnosis, tumor multicentricity, TNM stage, and disease-specific mortality." (PMID 29552294, 2018).
muscular atrophy (2 papers, 2018). The loss of muscle tissue due to inactivity or disease. "Here we have studied the role of agrin in preventing muscular atrophy in SMA as we hypothesized that stabilization of NMJs would improve the crosstalk between muscle fibers and MNs and thus delay disease progression, muscle atrophy and motor impairment." (PMID 29440993, 2018). "We conclude that increasing agrin function in SMA has beneficial outcomes on muscle fibers and NMJs as the agrin biological NT-1654 restores the crosstalk between muscle and MNs, delaying muscular atrophy, improving motor performance and extending survival." (PMID 29440993, 2018).
pancreatic ductal adenocarcinoma (2 papers, 2025). An infiltrating adenocarcinoma that arises from the epithelial cells of the pancreas. "In line with our observation, pancreatic ductal adenocarcinoma CSC appears to release extracellular vesicles (EVs) loaded in agrin that will bind to non-CSC via LRP4 to promote YAP activation and subsequently non-CSC reprogramming into CSC." (PMID 40771583, 2025).
papillary thyroid carcinoma (2 papers, 2019 to 2022). "Agrin (AGRN) has been described as a multifunctional heparan sulfate proteoglycan, which can regulate angiogenesis and has a board-ranging impact on the tumor microenvironment (TME) in HCC and papillary thyroid carcinoma (PTC)." (PMID 36046688, 2022).
small cell lung carcinoma (2 papers, 2018 to 2025). Small cell lung cancer (SCLC) is a highly aggressive malignant neoplasm, accounting for 10-15% of lung cancer cases, characterized byrapid growth, and early metastasis. "Second, the agrin–EGFR co‐expression observed in various pathologic grades of LUAD pertained to solid, papillary, and acinar adenocarcinomas but was not obvious in small cell lung cancers from an Asian cohort." (PMID 40165020, 2025).
subependymoma (2 papers, 2015 to 2016). Subependymoma is a rare and slow growing type of ependymoma, often presenting in middle-aged adults, found more commonly in men than in women, usually located in the fourth and lateral ventricles and manifesting with variable symptoms including headache, nausea, and loss of balance. "Although investigation of subependymomas reveals also no expression of agrin and dystroglycan and hence no formation of OAPs, these benign tumors are not comparable to the infiltrating astrocytomas." (PMID 27483250, 2016). "In subependymomas neither agrin nor alpha-dystroglycan were detected around blood vessels." (PMID 26115524, 2015).
amoebiasis (1 paper, 2023). "Most of the upregulated DEPs, except Thrombospondin 1, Agrin, and Syndecan-1, involved in the ECM-receptor interaction pathway were also enriched in the amoebiasis pathway." (PMID 38069077, 2023).
Anxiety (1 paper, 2022). Intense feelings of nervousness, tension, or panic often arise in response to interpersonal stresses. "The altered expression of four anxiety-related genes, c-Fos, Adora2a, BDNF, and AGRN were additionally confirmed by RT-qPCR." (PMID 35491423, 2022).
brain tumors (1 paper, 2014). "In contrast, loss of agrin deposition in the vasculature of brain tumors is accompanied by the loss of endothelial junctional proteins." (PMID 25107608, 2014).
coloboma (1 paper, 2012). An abnormality in which a part of a structure in one or both eyes is missing. "Overexpression of agrin in mice leads to ocular dysgenesis including anophthalmos, microphthalmos, adhesion of iris and lens to the cornea, and coloboma of the optic stalk by repressing Sonic Hedgehog signaling." (PMID 24955751, 2012).
congenital heart disease (1 paper, 2022). A heart disease that is present at birth. "Right ventricular (RV) biopsies were collected from 40 patients undergoing surgery for congenital heart disease and the expression of agrin and associated proteins was investigated." (PMID 35355976, 2022).
coronary heart disease (1 paper, 2023). "This study aimed to assess circulatory biomarkers related to these mechanisms [albumin, transthyretin, alanine aminotransferase (ALT), aspartate aminotransferase (AST), and C-terminal agrin fragment] and their relationship with muscle mass in people with coronary heart disease." (PMID 36891188, 2023).
depression (1 paper, 2024). "In an experimental model of the chronic unpredictable mild stressmice model of depression, multiple DXM injections (at a dosage of 5 mg/kg) to C57Bl/6 mice for 6 consecutive weeks reduced the mRNA level of the core basement membrane protein agrin by 1.5 times." (PMID 39051219, 2024).
developmental delay (1 paper, 2022). "Mutations in the signaling pathway of VAMP2 and AGRN impair proper signaling between the presynaptic and postsynaptic neurons, and can result in neurodevelopmental conditions known as global developmental delay (GDD)." (PMID 36176870, 2022).
dystroglycanopathy (1 paper, 2016). "In contrast, other forms of dystroglycanopathy usually exhibit markedly diminished or no binding for both laminin and agrin in muscle, together with defective muscular basement membrane compaction." (PMID 27807076, 2016).
epilepsy (1 paper, 2024). A brain disorder characterized by episodes of abnormally increased neuronal discharge resulting in transient episodes of sensory or motor neurological dysfunction, or psychic dysfunction. "To examine the role of agrin in SE-induced epilepsy, we injected exogenous agrin protein (1 μl, 50 μg/ml) into the lateral ventricle each day for 2 weeks after SE onset." (PMID 38783336, 2024). "We found that agrin infusion into ventricle promoted the development of SE-induced epilepsy which is dependent of Lrp4 in the astrocytes." (PMID 38783336, 2024). "A parsimonious interpretation is that SE induces over-release of agrin in the hippocampus, which binds to astrocytic Lrp4 and aggregates the development of SE-induce epilepsy." (PMID 38783336, 2024). "Our study identifies a vital role of agrin-Lrp4 signaling in regulating the development of SE-induced epilepsy." (PMID 38783336, 2024). "Together, these observations suggest that agrin promotes SE-induced epilepsy in an Lrp4-dependent manner." (PMID 38783336, 2024).
fibrosis (1 paper, 2020). the formation of excess fibrous connective tissue in an organ or tissue in a reparative or reactive process. "Other proteins such as TSP-1, OPN, proteoglycans lumican and agrin, and matricellular proteins SPARC and SMOC2 have a clear association with fibrosis in NAFLD patients and animal models." (PMID 33262757, 2020).
frontotemporal dementia (1 paper, 2013). Frontotemporal dementia (FTD) comprises a group of neurodegenerative disorders, characterized by progressive changes in behavior, executive dysfunction and language impairment, as a result of degeneration of the medial prefrontal and frontoinsular cortices. "We tested here the cognitive reserve hypothesis in patients with frontotemporal dementia (FTD), with or without pathogenetic granulin mutations (GRN+ and GRN-), and in presymptomatic GRN mutation carriers (aGRN+)." (PMID 24040338, 2013).
Hirschsprung disease (1 paper, 2026). Hirschsprung disease (HSCR) is a congenital intestinal motility disorder that is characterized by signs of intestinal obstruction due to the presence of an aganglionic segment of variable extent in the terminal part of the colon. "The secretory heparan sulphate proteoglycans perlecan, agrin, collagen18A1 are expressed in the periganglionic sheath of enteric ganglia in resectates of Hirschsprung's disease patients and non‐Hirschsprung controls." (PMID 41555564, 2026).
Insulin resistance (1 paper, 2022). Increased resistance towards insulin, that is, diminished effectiveness of insulin in reducing blood glucose levels. "Genes commonly upregulated in the IR-iPSCs when compared to each IS-iPSC group include EGR1 and MFGE8, which were previously associated with insulin resistance, as well as CD74, SEMA6B, SLFN13, TMEM151B, SLC22A17, and AGRN." (PMID 35987697, 2022).
metastatic cancers (1 paper, 2017). A carcinoma which has spread from the original site of growth to another anatomic site. "For example, in a study of mutational profiles in metastatic breast cancers, AGRN was more frequently mutated in metastatic cancers compared with early breast cancers." (PMID 28912426, 2017).
metastatic melanoma (1 paper, 2024). A melanoma that has spread from its primary site to another anatomic site. "Interestingly, besides amyloidogenic proteins, we identified Agrin in both metastatic melanoma and PDAC cells, suggesting that this protein could be part of the amyloid plaques secreted by cancer cells." (PMID 38199984, 2024).
myocardial ischemia (1 paper, 2023). A disorder of cardiac function caused by insufficient blood flow to the muscle tissue of the heart. "In addition, AGRN is a crucial regulatory factor in the epithelial-mesenchymal transition in epicardium, promoting epicardial cell proliferation, reducing myocardial ischemia-reperfusion injury and improving cardiac function." (PMID 37841281, 2023).
parasite (1 paper, 2025). "This transition may have activated DAMP signaling through its ability to perform chondroitin sulfate and heparan sulfate proteoglycan binding in the host, leading to or possibly caused by genes such as AGRN, shown to be expressed as part of the plasma membrane during GI parasite infections in sheep." (PMID 40906414, 2025).
Parkinson disease (1 paper, 2022). A progressive degenerative disorder of the central nervous system characterized by loss of dopamine producing neurons in the substantia nigra and the presence of Lewy bodies in the substantia nigra and locus coeruleus. "Similarly in Parkinson’s disease, agrin was shown to associate with α-synuclein in Lewy bodies of the substantia nigra." (PMID 35948834, 2022).
respiratory failure (1 paper, 2014). The significant impairment of gas exchange within the lungs resulting in hypoxia, hypercarbia, or both, to the extent that organ tissue perfusion is severely compromised. "The agrin/Lrp4/MuSK signaling pathway is essential for survival as mice deficient for either agrin, Lrp4, MuSK or Dok-7 die at birth because of respiratory failure." (PMID 24520420, 2014).
sarcoma (1 paper, 2015). A usually aggressive malignant neoplasm of the soft tissue or bone. "The same effect was achieved by replacing exogenous agrin with ECM purified from Engelbreth-Holm-Swarm (EHS) mouse sarcoma, where laminin, collagen IV, heparan sulfate proteoglycan (a class of molecules that includes agrin), and nidogen/entactin are the major components." (PMID 24777283, 2015).
Senile plaques (1 paper, 2022). Senile plaques are extracellular deposits of amyloid in the gray matter of the brain. "In AD post-mortem brain tissue, agrin, glypicans and syndecans, but not perlecan, have been found in NFTs, and senile plaques." (PMID 36564747, 2022).
Stroke (1 paper, 2021). Sudden impairment of blood flow to a part of the brain due to occlusion or rupture of an artery to the brain. "Due to that, Agrin can be considered a potential therapeutic target for the treatment of stroke and other diseases of the nervous system." (PMID 34113618, 2021). "Recently, the effect of Agrin on neurorepair and synaptogenesis after stroke was investigated." (PMID 34113618, 2021).
systemic lupus erythematosus (1 paper, 2023). An autoimmune multi-organ disease typically associated with vasculopathy and autoantibody production. "The correlation between AGRN levels and systemic lupus erythematosus (SLE) disease activity index score (SLEDAI) was further analyzed." (PMID 37841281, 2023).
tongue neoplasm (1 paper, 2018). A neoplasm (disease) that involves the tongue. "Tongue neoplasms are in the top five predicted protein diseases related to agrin partners." (PMID 29872149, 2018).
tubulointerstitial nephritis (1 paper, 2020). "Notably, the mix of ADAMTS5-affected matrix proteins was enriched in basement-membrane components including laminins (LAMA/LAMB/LAMC), collagen-6 (COL6A1/A2), collagen-12 (COL12A1), AGRN, nidogen-1 (NID1), and TINAG (tubulointerstitial nephritis Ag)." (PMID 32917786, 2020).